IL6 (interleukin 6)
Diseases named in the same sentence as IL6 in open-access papers (continued):
Sharing a sentence is not in itself a finding about the gene and the disease.
encephalitis (87 papers, 2008 to 2026). An acute inflammatory process affecting the brain parenchyma. "Increased blood interleukin 6 (IL-6) levels in the acute stage of encephalitis are associated with poor prognosis." (PMID 35204857, 2022). "In our study human neuronal cells infected with the pathogenic C genotype virus isolated from a case of encephalitis secreted significantly higher amount of IL-6, IL-8 and IP-10 cytokines as compared to other genotypes at 12 hpi." (PMID 34493781, 2021). "We chose markers that have already been associated with viral encephalitis and neurodegenerative diseases, including tumor necrosis factor alpha (TNFα), interleukin 6 (IL6), and interleukin 1 β (IL1β)." (PMID 33407600, 2021). "The release of cytokines such as TNF-α, interleukin-1β (IL-1β) and interleukin-6 (IL-6) is closely associated with encephalitis." (PMID 31652591, 2019). "Following CHPV infection expression levels of TNF-a, CCL2 and IL-6 were found to increase that was previously implicated in playing decisive roles in encephalitis has decreased significantly after (-)-25b treatment." (PMID 30001342, 2018). "Infants with primary HHV-6 infection-associated encephalitis show higher serum and CSF levels of IL-6." (PMID 27538995, 2017). "Because IL-6 in the CSF is a representative cytokine reflecting inflammation in the central nervous system, excessive production of inflammatory cytokines was likely the cause for developing encephalitis in the present case." (PMID 32620173, 2020). "It is possible that robust IL-6 responses may lead to a cytokine “storm” via IL-6 receptor signaling, resulting in more severe clinical pathology such as hepatic inflammation, encephalitis, and risk for death." (PMID 25756647, 2015). "Indeed, interleukin-6 (IL-6) leads to the excessive production of vasopressin in the hypothalamus in patients with meningitis or encephalitis, often causing SIADH." (PMID 19787076, 2008). "We next utilized neutralizing antibodies to evaluate the roles of CXCL1 and IL-6 in EV-A71 encephalitis." (PMID 39679722, 2025). "Alteration of CCL-4, CCL-17, CCL-20, CXCL10, CXCL-13, and TNF-α, IFN-γ, IL-2, IL-4, IL-5, IL-6, IL-9, IL-10, and IL-22 have been reported in the CSF or serum/plasma of patients with encephalitis." (PMID 40717731, 2025). "Menopause is a physiological condition that triggers encephalitis, leading to the production of cytokines such as interleukin-1β (IL-1β), IL-1α, and IL-6." (PMID 40292265, 2025). "A previous study suggested that astrocyte-derived IL-6 plays an important role in EV-A71 encephalitis; therefore, we utilized αCXCL1 and αIL-6 for treatment." (PMID 39679722, 2025). "Elevated S-CKs levels can serve as diagnostic indicators for acute viral encephalitis in children; there are reports of high levels of TNF-α and IL-6 in the CSF." (PMID 39995678, 2025). "This meta-analysis serves as evidence that encephalitis patients had greater CSF concentrations of IL-6, IL-8, IL-10, CXCL10, and TNF-α when compared to controls." (PMID 36048783, 2022). "It is also known that patients infected with human orthopneumovirus and presenting neurological symptoms such as encephalitis and encephalopathies, have elevated levels of the proinflammatory cytokines IL-6, IL-8, CCL2, and CCL4 in CSF samples." (PMID 36591299, 2022). "The CSF levels of the IL-6 in encephalitis patients are significantly higher than controls (SMD, 1.72; 95% CI, 0.79–2.66; P < 0.001)." (PMID 36048783, 2022). "Compared to HC, patients with encephalitis or encephalopathy presented elevated IL-6 and IL-8 in both serum and CSF, whereas IL-10, IL-1RA, IL-1b and MIG were elevated only in serum, and MCP1 only in CSF (data not shown)." (PMID 35479062, 2022). "According to the analyses, patients with encephalitis had higher CSF amounts of IL-6, IL-8, IL-10, CXCL10, and TNF-α than healthy controls." (PMID 36048783, 2022).
encephalitis (continued). "There was also a positive correlation between CSF OPN levels and CSF IL-6 levels in anti-NMDAR encephalitis patients in acute stage." (PMID 33250837, 2020). "Genotype and allele frequencies of IL-1β, IL-4, IL-6, IL-10, and IL-17 in anti-NMDAR encephalitis and control groups." (PMID 33362683, 2020). "Increased levels of inflammatory factors such as interleukin 6 in the blood suggest the activation of inflammation in peripheral circulation in patients with anti-NMDAR encephalitis." (PMID 31156383, 2019). "According to previous studies on cerebrospinal fluid (CSF) chemokines in EV71 patients with encephalitis or meningoencephalitis (ME), CSF IL-6, IL8, CCL5 and CXCL10 concentrations were significantly higher compared to patients with febrile convulsion (FC)." (PMID 31575039, 2019). "The encephalitis group and the control group generally showed lower cytokine levels in CSF than in serum, with exceptions for IL-6 and IL-8 in the encephalitis group and MCP-1 and IP-10 for both groups." (PMID 30470234, 2018). "Higher IL-6 and IL-10 levels are frequently measured in several neurological disorders, including encephalitis." (PMID 27538995, 2017). "In multivariate analysis, plasma IL-6 was significantly increased in patients with FS compared to those with severe acute encephalitis, suggesting that IL-6 is activated during the acute stage of a febrile seizure." (PMID 27068222, 2016). "Increased serum levels of pro-inflammatory cytokines, IFN-γ, IL-6, and TNFα are observed in patients with EV71-associated encephalitis and pulmonary edema compared to patients with uncomplicated HFMD." (PMID 26181772, 2015). "Consistent with clinical features of EV71 patients with encephalitis and PE, who are presented with higher levels of the proinflammatory cytokines in blood, IL-6, IL-1β and TNF-α were induced in EV71-infected MDMs." (PMID 22994237, 2012). "IL-6 levels provide particularly valuable information with respect to the diagnosis and severity of encephalitis or encephalopathy." (PMID 18652703, 2008). "Moreover, in FIRES Th1-associated cytokines and chemokines, as well as IL-6, CCL2, CCL19, and CXCL1, resulted elevated when compared to the levels observed in encephalitis, which involved a broader network of cytokines/chemokines." (PMID 38078329, 2023). "In addition, the serum/plasma levels of the TNF-α were increased in encephalitis patients, but serum/plasma concentration of the IL-6, IL-10, CXCL10, and CXCL13 remained unchanged." (PMID 36048783, 2022). "Because EV71 patients with encephalitis have been reported to have increased TNFα and IL-6 levels, we also investigated whether the gliosis-associated inflammatory markers would also be decreased in sera collected from these mice treated with the antibody." (PMID 35399111, 2022). "The cerebrospinal fluid level of interleukin 6 reflected the severity of the encephalitis well." (PMID 32620173, 2020). "IL-2, CXCL10, CCL3, IL-10, CCL22, and IL-6 may represent new biomarkers in patients with anti-NMDAR encephalitis." (PMID 33408682, 2020). "The CSF level of IL-6 reflected the severity of the encephalitis well." (PMID 32620173, 2020). "A published review of CSF cytokines in children also found Th1 cytokines to be associated with viral encephalitis and CXCL13 and IL6 to be associated with NMDAR-antibody associated encephalitis and non-herpetic limbic encephalitis, respectively." (PMID 32116981, 2019). "In patients with encephalitis accompanied by hyponatremia, elevated IL-6 or urinary β2-microglobulin (β2MG), and exacerbations such as sudden somnolence, delirium, confusion, and seizures, the possibility of secondary MERS should be investigated, in addition to the progression of encephalitis." (PMID 31764808, 2019). "As to viral encephalitides, increased CSF IL-6, IL-7, and IL-13 may differentiate viral encephalitis from autoimmune NMDAR encephalitis in children." (PMID 29670611, 2018).
encephalitis (continued). "The elevated levels of IL-10, IL-6, IL-8, TNFα (cytokines) and CCL2 and CXCL9 (chemokines) in monocytes may help in predicting the pathogenicity of CHPV causing encephalitis and possible entry into the central nervous system." (PMID 27628855, 2016). "This might be a characteristic of our model, as IL-6 release by both infiltrating macrophages and resident microglia has been observed in previous virus-induced encephalitis models, and has been shown to contribute to the precipitation of seizures." (PMID 27955671, 2016). "IL-6 was found as an indicator of EV-A71 encephalitis with pulmonary edema." (PMID 25412347, 2014). "IL-6 >70 pg/ml was the best predictor of EV71 encephalitis with pulmonary edema." (PMID 25391156, 2014). "It was previously reported in Sindbis virus-induced encephalitis that the infected astrocytes in the brain may be the source of pro-inflammatory cytokines such as IL-6 and TNF-α." (PMID 24086645, 2013). "IL-6 > 70 pg/mL was found to be the best predictor of EV71 encephalitis with PE." (PMID 22956971, 2012). "For instance, βArr2 inhibited the pro-inflammatory cytokines TNF-α and IL-6 and activation of transcription factor NF-κB, increased the expression of anti-inflammatory cytokines IL-10 and IL-4 in microglia for enhancing neurological function in encephalitis mice." (PMID 34787064, 2022). "Thus, IL-17A/IL-6 co-activation in anti-NMDAR encephalitis may be a key factor in the pathogenesis of the disease and the production of intrathecal antibodies." (PMID 35937071, 2022). "Animals lacking IL-1β, IL-6, or IL-12 may be resistant to fatal encephalitis or seizures caused by encephalitis, or have reduced neurological severity scores." (PMID 29670611, 2018). "Cerebrospinal fluid (CSF) analysis revealed inflammatory changes featuring markedly elevated IL-6 levels, while serological and imaging studies excluded infection, supporting a diagnosis of ICI-related encephalitis." (PMID 41836426, 2026). "Meanwhile, key inflammatory mediators (MCP1, IL1β, IL6, TNFα) were significantly elevated in NCG-hSTAT2+/+ mice during viral neuroinvasion, likely driving encephalitis pathogenesis." (PMID 40855992, 2025). "Our results align with a RVFV encephalitis model using strain CC057 mice, where levels of IL-10, IP-10, IL-6, MIG and MCP-1 were shown to be elevated in plasma on days 5–8 post-infection." (PMID 38140610, 2023). "The alteration in the concentration of the different chemokines, such as CXCL10, CXCL-13, CCL-4, CCL-17, CCL-20, and cytokines, including IL-2, IL-4, IL-6, IL-9, IL-10, and IFN-γ have been observed in encephalitis patients." (PMID 36048783, 2022). "Proinflammatory factors IL-6, TNF-α, IL-1β were found significantly higher in patients with encephalitis and NPE than those with mild disease." (PMID 36386168, 2022). "This meta-analysis provides evidence for higher CSF concentrations of IL-6, IL-8, IL-10, CXCL10, and TNF-α in encephalitis patients compared to controls." (PMID 36048783, 2022). "sCD146 levels in the CSF of patients with the acute stage anti-NMDAR encephalitis were significantly increased compared with controls and accompanied by increases in TNF-α, IL-6 and IL-10." (PMID 34220828, 2021). "Significant positive correlations were found between sCD146 levels and IL-10 (r=0.479, p=0.021), IL-6 (r=0.452, p=0.031), and MMP2 (r=0.415, p=0.049) in the CSF of anti-NMDAR encephalitis patients in the acute stage." (PMID 34220828, 2021). "At the same time, our findings regarding OPN, IL-6, IL-10, and TNF-α raise the question of possible involvement of T cells in anti-NMDAR encephalitis." (PMID 33250837, 2020).
encephalitis (continued). "We did not identify any significant differences in SNP genotypes of IL-1β, IL-4, IL-6, IL-10, and IL-17 between anti-NMDAR encephalitis and control groups." (PMID 33362683, 2020). "Other markers (e.g., IL6, TNFA, IL2 and IL4) were also up-regulated and are increased in the CNS of patients with viral encephalitis and autoimmune epilepsy." (PMID 32225060, 2020). "Concentrations of IL‐1β, IL‐6, and IL‐17A dramatically increased in anti‐NMDAR encephalitis group compared with controls (p < 0.0001)." (PMID 31313506, 2019). "Here, we demonstrated that the CSF level of IL-6 was significantly increased and positively correlated with CSF mtDNA levels in anti-NMDAR encephalitis." (PMID 30792710, 2019). "In descending order, CSF TNF-α, IL-10, IFN-α, IL-6, CXCL13 and CXCL10 had the best sensitivity (>79.1%) when all encephalitis patients were included." (PMID 27575749, 2016). "We observed that TNF-α, IL-10, IFN-α, IL-6, CXCL10 and CXCL13 demonstrated >79.1% sensitivity in patients with encephalitis using control 95th centile as cut off (specificity 95%)." (PMID 27575749, 2016). "In our cohort of encephalitis, the Th1 (CXCL10 & TNF-α), T reg (IL-10), B cell (CXCL13) related cytokine/chemokines, and cytokines with broad spectrum of activities including IL-6 and IFN-α, were elevated in more than 75% of the cases." (PMID 27575749, 2016). "High levels of proinflammatory cytokines, such as Interleukin 6 (IL-6), Tumor necrosis factor α (TNF-α) and Interleukin-1β (IL-1β), have been found in EV-A71 patients with pulmonary edema (PE) and encephalitis." (PMID 25412347, 2014). "The IL-1β, IL-6, and TNF-α levels in fatal patients with encephalitis plus PE were significantly higher than those of uncomplicated patients." (PMID 22956971, 2012). "Various inflammatory cytokines/chemokines, such as IL-6, IL-17A, CXCL13 in cerebrospinal fluid, and IL-2 in plasma, and miRNAs (like e.g., Let-7b) in plasma, have been shown to play important roles in the process of anti-NMDAR encephalitis." (PMID 40948637, 2025). "Similarly, elevated levels of IL-1β, IL-2, IL-6, IL-8, IL-15, IL-17, and IL-18 have been detected in cases of GBS, active MS, encephalitis, inflammatory myopathies, viral and bacterial meningitis, and stroke." (PMID 40717731, 2025). "Several studies have shown that IL-6 is elevated in the CSF of patients with anti-NMDAR encephalitis but not in anti-LGI1 encephalitis, often accompanied by increased IL-17A and CXCL13, suggesting a subtype-specific pattern of Th17-driven inflammation." (PMID 41041342, 2025). "It has been reported that high levels of cytokines such as IL-1β, IL-6, IL-10, and IFN-γ are correlated with clinical severity in patients with pulmonary oedema and encephalitis, indicating that the immune response of the hSCARB2 mouse model was similar to that of humans." (PMID 34044752, 2021). "In earlier reports, levels of IL-1β, IL-6 and TNFα were found to be significantly elevated in fatal EV-A71 patients with encephalitis and pulmonary oedema, when compared to patients with no complications." (PMID 32123257, 2020). "Studies have shown that increased IL-6 in CSF and brain tissue could facilitate production of intrathecal anti-NMDAR autoantibody in encephalitis." (PMID 30369903, 2018). "In this study, we found that the changes in IL-6 correlated with changes in YKL-40, suggesting that IL-6 may contribute to YKL-40 expression and the autoantibody-induced neurological deficits observed in anti-NMDAR encephalitis." (PMID 30369903, 2018). "Studies with IL1R1 knockout mice have demonstrated that IL1 is critical for limiting WNV-induced encephalitis in the murine model, purportedly via a T cell activation mechanism and mice inoculated intraperitoneally with WNVNY99 had upregulation of IL6 and IL12 transcripts." (PMID 27267361, 2016).
encephalitis (continued). "In line with a previous study of viral encephalitis we found higher relative levels of CCL-2 and IL-6 in the CSF than serum and higher levels of CCL-5 in serum; in our study this was also found in those with immune-mediated and unknown aetiologies." (PMID 26808276, 2016). "In particular, it has been found that interleukin 6 (IL-6) and tumor necrosis factor (TNF)-alpha are increased in severe cases of ANE, showing the significance of the inflammatory reaction in the pathogenesis of the brain damage typical in these types of encephalitis." (PMID 40757726, 2024). "Previous studies have found that IL-6, IL-1β, IL-8, tumor necrosis factor-alpha (TNF-α), monocyte chemotactic protein-1 (MCP-1), and granulocyte-macrophage colony-stimulating factor (GM-CSF) was highly elevated either in serum or CSF of patients with COVID-19 related encephalitis." (PMID 37384050, 2023). "A clinical study found that the serum levels of eotaxin, IFN- γ, IL-15, IL-6, IP-10, and TNF-α in the confirmed encephalitis patients were elevated remarkably before clinical deterioration, which might be related to a potential association with the development of encephalitis." (PMID 35782112, 2022). "It was also noted that the levels of serum eotaxin, IFN-γ, IL-15, IL-6, IP-10, and TNF-α were significantly elevated before clinical deterioration in the confirmed encephalitis patient, suggesting the roles of these cytokines in the development of encephalitis." (PMID 35782112, 2022). "Pooled data demonstrated that the serum/plasma levels of the IL-6 are not significantly higher (SMD, 0.56; 95% CI, -0.41–1.52; P = 0.26) in encephalitis patients (n = 111) than controls (n = 94)." (PMID 36048783, 2022). "Studies have reported that the pro-inflammatory cytokine IL-6 is elevated in the CSF of patients with anti-NMDAR encephalitis, but this increase is not remarkable in patients with anti-LGI1 encephalitis." (PMID 35937071, 2022). "In addition, blood eosinophil leukocyte chemotactic factor, IFN-γ, IL-15, IL-6, interferon gamma-induced protein-10, and tumor necrosis factor-α were significantly elevated before disease deterioration in a non-fatal encephalitis SFTS patient, which may be due to encephalitis development." (PMID 36406394, 2022). "The analysis showed that there was a statistically significant correlation of CSF cell-free mtDNA with IL-6 (r = 0.307, p = 0.041), but neither with IL-10 (r = −0.085, p = 0.319) nor TNF-α (r = −0.050, p = 0.391) in the acute stage of anti-NMDAR encephalitis." (PMID 30792710, 2019). "However, CSF levels of IL-6 were not significantly different among patients with different clinical EV71 syndromes, PE, encephalitis and/or poliomyelitis-like syndrome, and aseptic meningitis during the acute stage of CNS involvement." (PMID 22956971, 2012).